TDP2 (tyrosyl-DNA phosphodiesterase 2)
Diseases named in the same sentence as TDP2 in open-access papers (continued):
Sharing a sentence is not in itself a finding about the gene and the disease.
infection (6 papers, 2014 to 2023). The state of being infected such as from the introduction of a foreign agent such as serum, vaccine, antigenic substance or organism. "Only HPGD, PACS1, and TDP2 showed involvement in biological pathways, including metabolism, infection, and DNA repair-related pathways." (PMID 37091184, 2023). "We infected the WT and KO TDP2 hRPE-1 cells with either poliovirus or CVB3 at a multiplicity of infection (MOI) of 3 and carried out single cycle growth analyses to determine virus growth kinetics." (PMID 32023921, 2020). "Unlinking of VPg has been shown not to be necessary for the initial round of translation and replication of the incoming RNA template, indicating that the requirement for TDP2 activity occurs at a later step during infection." (PMID 32023921, 2020). "We carried out an 8 h infection time course for poliovirus in WT and KO TDP2 RPE cells, collected cell lysates at 2 h intervals, TRIzol-extracted the total cellular RNA, and quantified the viral RNA content by qRT-PCR." (PMID 32023921, 2020). "Many proteins, including nucleolin, hnRNP A1, PTBP1, La, Sam68, hnRNP K, hnRNP C1/C2, SRSF3, and TDP2, that are relocalized as a result of infection have known functions in the replication cycle of picornaviruses." (PMID 26150805, 2015). "This suggestion isin line with the recent observation that the TDP2 enzyme is relocated to cytoplasmic sitesdistal to the viral RNA late in infection, which correlates with the shift from RNA translation/replication to RNAencapsidation." (PMID 24243841, 2014). "The infection-induced fever may increase viral load in the host by inhibiting the nucleases, giving the virus a chance to replicate its genome using TDP2, which has been shown to facilitate viral replication." (PMID 34065967, 2021). "This hypothesis is based on the fact that poliovirus has been demonstrated to re-localize TDP2 from the nucleus to the cytoplasm at mid times of infection." (PMID 32023921, 2020). "To determine if an alternative source of VPg unlinkase activity was activated at late times of infection, we generated lysates from either WT or KO TDP2 mock- or poliovirus-infected hRPE-1 cells that were collected at 6 hpi and used them to carry out a VPg unlinkase assay." (PMID 32023921, 2020). "In this study, we characterized the role of host cell protein tyrosyl-DNA phosphodiesterase 2 (TDP2) activity, also known as VPg unlinkase, in picornavirus infections in a human cell model of infection." (PMID 32023921, 2020). "Furthermore, several host cellular DNA repair proteins, such as tyrosyl-DNA phosphodiesterase 2 (TDP2), DNA polymerase (Pol), flap endonuclease 1 (FEN1), and DNA ligases, are required for cccDNA synthesis in de novo infection and intracellular amplification." (PMID 34931766, 2021). "Independent of understanding the precise role of TDP2 during infection, this protein provides an additional example of nuclear-resident proteins being used in diverse ways, even during the very initial steps in the infectious cycles of picornaviruses." (PMID 26150805, 2015). "Our data demonstrated that the delay in protein production that occurs at mid-times of infection in the absence of TDP2 is not rescued by blocking RNA packaging using the inhibitor hydantoin, suggesting that encapsidation of VPg-linked RNA is not responsible for the phenotype." (PMID 32023921, 2020). "The interpretation of this is that TDP2 may be excluded from sites of replication when VPg unlinkase activity is no longer required at late times of infection." (PMID 32023921, 2020). "While previous studies used mouse embryonic fibroblast cells (MEFs) to address whether TDP2 is required for virus replication, there are certain aspects of this model that do not faithfully recapitulate human infections with picornaviruses." (PMID 32023921, 2020).
infection (continued). "Moreover, TDP2 forms a distinctive pattern in HeLa cells late during the infection in which the protein is localized adjacent to but does not co-localize with markers of virus replication complexes." (PMID 32023921, 2020).
neurological disorders (4 papers, 2018 to 2024). "Patients with neurologic disorders such as intellectual disability, seizures, and ataxia have mutations in TDP2." (PMID 30555231, 2018).
TDP2 also shares sentences with these, for which no sentence is quoted: cerebellar ataxia (2 papers); dyslexia (2); neurodegenerative disease (2); acute leukemia (1); colorectal cancer (1); developmental delay (1); epilepsy (1); genetic disorder (1); hereditary neurological disease (1); Huntington disease (1); inflammatory bowel disease (1); intellectual impairment (1); melanoma (1); mitochondrial disease (1); neuroblastoma (1); osteosarcoma (1); pancreatic cancers (1); prostate tumors (1); renal carcinoma (1); renal cell carcinoma (1); retinoblastoma (1); Spastic paraplegia (1); spinocerebellar ataxia 23 (1); Synthesis (1).